CXCL13 (C-X-C motif chemokine ligand 13)
Diseases named in the same sentence as CXCL13 in open-access papers (continued):
Sharing a sentence is not in itself a finding about the gene and the disease.
tumor (continued). "CXCL13/CD103/CD8 triple-positive TILs have previously been identified with B cell recruitment, TLS formation, neo-antigen burden and cytolytic gene signatures in human tumors and TIM-3 expression has been identified on CD39/CD103 double-positive tumor-reactive CD8-positive T cells." (PMID 36341460, 2022). "In concurrence with NanoString analysis of our own tumor samples, these included IFN-γ signaling genes STAT1, CXCL10, and IDO1; antigen presentation molecules HLA-DQA1 and HLA-DRB1; important T cell molecules GZMB and IL7R; and B cell–related molecules CD79A and CXCL13." (PMID 35132960, 2022). "Within the lag period of 0–9 months, most markers showed stronger discrimination for serous tumours as compared to tumours with other or unspecified histology, with notable exceptions for WISP1, and CXCL13 which showed higher AUCs for the tumours of non-serous histology." (PMID 35031764, 2022). "Interestingly, although compared to 4T1 and 4T1-pCDH, 4T1-CXCL13-1 or 4T1-CXCL13-2 tumors showed decreased growth rate, we did not observe complete tumor regression, which suggested attenuated antitumor activity of CXCL13 in BALB/cA-nu mice." (PMID 35693216, 2021). "On one hand, CXCL13 attracts immunosuppressive cells to mediate immune suppression or evasion, leading to tumor progression, while on the other hand, the CXCL13/CXCR5 axis elicits tumoricidal immunity signaling to escape tumor immunosurveillance in some cancer types." (PMID 34947813, 2021). "In addition, the CXCL13/CXCR5 axis also potentiates the crosstalk between tumor cells and lymphocytes or non-lymphocytes, shaping a complex TME." (PMID 34947813, 2021). "To test our hypothesis, we first defined the area of TLS-like lesion (see “Methods” section) and then evaluated the abundance of TFH-like (CXCL13+CD4+), B (CXCR5+CD20+), and TRM-like (CD103+CD8+) cells within the TLS-like lesions of archival tumor tissue samples using multiplexed IF." (PMID 34663810, 2021). "Tfh cells recruited CD8+ T cells and B cells by secreting C-X-C motif chemokine ligand 13 (CXCL13), and promoted the maturation of B cells into antibody-producing plasma cells by secreting interleukin 21 (IL-21), thereby promoting the formation of an immunoactive tumor microenvironment." (PMID 34359579, 2021). "We hypothesized that CXCL13 expressed in T cells and CD79A and IGLL5 expressed in B cells could affect the expression of LHFPL2 gene through the CD45 signaling pathway, acting on macrophages, thus jointly playing a role in tumor regulation." (PMID 34900411, 2021). "Moreover, while intratumoral artLCMV-TRP2 treatment of Ctrl mice promoted tumor control and cured four out of nine mice in long-term, Cxcl13-Cre Il33fl/fl mice failed to control the tumors." (PMID 34354077, 2021). "Importantly, current expression of CXCL13 as determined by the tdTomato reporter was significantly increased in tumor fibroblasts following artLCMV-TRP2 treatment, but was not affected in TDLNs." (PMID 34354077, 2021). "Mouse Tfh cells do not secrete CXCL13; therefore, we could not simulate the anti-tumor process of human CXCL13 secreting Tfh cells in a mouse model." (PMID 34359579, 2021). "CXCL13 is also produced by human bone marrow endothelial (HBME) cells, Tfh that have infiltrated into tumor tissues, PD1+ CD8+ T cells, the TGFβ-dependent CD103+CD8+ tumor-infiltrating T-cell (TIL) subpopulation, neoplastic T cells, and several types of tumor cells." (PMID 34947813, 2021). "The results showed CXCL13 expression was higher in tumor tissues, compared to the normal tissues." (PMID 32669964, 2020). "Furthermore, in vivo neutralization of CXCL10 or CXCL13 dampened the therapeutic effect of abemaciclib, indicating that CXCL10-mediated CD8+T cell infiltration and CXCL13-mediated B cell infiltration paly crucial roles in abemaciclib induced tumor suppression." (PMID 32929370, 2020).
tumor (continued). "Thus, CXCL13 and the immune cells that produced this chemokine in the NSCLC tumor microenvironment may represent novel biomarkers for response to targeted PD1/PD-L1 therapy." (PMID 31354634, 2019). "The identification of autocrine and paracrine interactions between the tumor microenvironment and cancer cells mediated by CXCL13 highlights how autonomous and non-autonomous mechanisms contribute to the development of the cancer phenotype and the dissemination of cancer cells to metastatic sites." (PMID 31354634, 2019). "Furthermore, we have shown that the co-expression of gene sets that contain CXCL13 and the gene sets that contain MMP1 is affected by ER status too, in addition to tumor grade which couldn’t have been elicited in a typical univariate DCX analysis." (PMID 29297310, 2017). "Notably, all the correctly classified FDC-S cases were positive for at least two markers among CXCL13, CD21, CD35, FDCSP and SRGN; this information could be easily applicable in the routine diagnosis of this tumor." (PMID 28145886, 2017). "Furthermore, serum CXCL13 and GPS discriminated patients at risk of treatment failure among patients with low tumor burden (stage I/II) and non-detectable EBV DNA." (PMID 25966773, 2015). "They concluded from their IHC data that the tumor was not the primary source of CXCL13." (PMID 24762633, 2014). "In the case of primary intraocular lymphoma, tumor cells expressed CXCR5, and adjacent non-cancerous ocular cells expressed CXCL13, suggesting that these ocular cells might be directing tumor growth." (PMID 23936541, 2013). "This promotion of cell growth could be coming from high levels of circulating CXCL13 produced elsewhere in the body, or from CXCL13 produced locally to the tumor, either by tumor cells themselves or by local nontumor cells." (PMID 21490903, 2010). "Importantly, we did not observe significant numbers of tumour-infiltrating leukocytes expressing CXCL13 or CXCR5." (PMID 18781150, 2008). "Furthermore, gemcitabine combined with local injections of CXCL13 and CCL21 into tumors in a murine model of pancreatic cancer-induced TLSs enhanced CD8+ T cell infiltration, decreased FOXP3+ regulatory T cells, and reduced tumor size compared to the vehicle-treated group." (PMID 41029827, 2025). "In addition to CXCL13 involved in inducing the formation of TLSs, CXCL12 was also found to be closely related to the formation of TLSs, and the expression of CXCL12 features could effectively promote the enrichment of TLSs in the tumor microenvironment." (PMID 40612858, 2025). "From the correlation, CXCL13 might not reflect the tumor stemness well in Pan-Gyn." (PMID 38459390, 2024). "In addition, along with well-established clinico-pathological factors (positive nodal status and large tumor diameter), the lack of CXCL13 expression and the expression of MUC1 in the tumor bed were identified as risk factors that are strongly associated with worse RFS and OS, respectively." (PMID 36765559, 2023). "Interestingly, the CXCL13+ CD8-Tterm.ex cluster displayed the highest clonality score among all CD8+ T cell clusters, as quantified by the STARTRAC clonal expansion index, likely reflecting the presence of clonally expanded, tumor antigen–specific T cell clones." (PMID 37655659, 2023). "The selective expression of CCR5 and CXCL13 in neoantigen-specific T cells further suggests that a key feature of CPI-responsiveness is the ability to sustain ongoing priming and recruitment of tumour reactive T cells supported by CXCR5+ lymphocytes, which may include T and B cells." (PMID 33508232, 2021). "Thus, we cannot exclude the possibility that most of the suggested biomarkers of PCNSL (such as IL-6, IL-10 and CXCL-13) and soluble receptor proteins (such as sCD27 and sIL-2R) were more abundant in PCNSL patients because they had originated in PCNSL tumor tissue." (PMID 29299134, 2017).
tumor (continued). "Importantly, CXCL13 was found to be the most sustained chemokine expressed, not decreasing dramatically even after 24 hours in culture without stimulation outside of the tumor." (PMID 24762633, 2014). "Some controversy exists as to whether or not CXCL13 is produced by the tumor cells themselves." (PMID 24762633, 2014). "In some of these cancers, tumor cells were shown to express both CXCL13 and CXCR5, suggesting a possibility for autocrine interactions, or CXCL13 was shown to be expressed in tissue surrounding tumors, raising the possibility that it could be directing the metastasis of tumor cells." (PMID 21490903, 2010). "In our study, we observed a slight increase in the expression of IL-17A, IL-6, and CXCL13 following PD-1 signaling activation, and no inhibitory effect on IFN-γ and TNF-α, which are downregulated in tumor T cells." (PMID 40825269, 2025). "Furthermore, the presence of CXCL13+ T cells may indicate a pre-existing immune activation state within the TME, characterized by efficient antigen presentation and immune cell recruitment, thereby priming the tumor for enhanced immune surveillance and therapeutic responses." (PMID 40464813, 2025). "We also confirm that the modifications made to the LVV have not compromised the tumor-killing efficacy of engineered cells overexpressing CD93, CD40L, and CXCL13." (PMID 41295503, 2025). "We found an unfavorable association between improved clinical outcomes in ICI-treated NSCLC and an elevated density of CXCL13+ cells in non-TLS regions, including the tumor, non-tumor, and invasive margin, as well as solely the NT (T+NT+IM, NT)." (PMID 38398098, 2024). "CCL5 was found to be remarkably elevated in tumor tissues collected from PTC patients coexistent with HT than those without HT, and CXCL9, CXCL10, CXCL11, and CXCL13 were also reportedly upregulated in thyroid tissues from HT patients." (PMID 38137348, 2023). "Here, single cell transcriptomics and imaging mass cytometry analysis of luminal breast tumours with or without exhausted T cells suggests distinct patterns of PD-1 and CXCL13 expression in T cells, and of MHC-I, but not PD-L1, expression in tumour cells." (PMID 36609566, 2023). "When the tumor cell has no endogenous CXCR5 expression, CXCL13 secretion in the tumor microenvironment can chemoattract CXCR5+ immune cells and trigger antigen-specific antitumor immunity." (PMID 35693216, 2021). "Tumor growth and survival were similar in PBS-injected Cre-negative littermate Ctrls and Cxcl13-Cre Il33fl/fl mice." (PMID 34354077, 2021). "On the contrary, CXCL4, CXCL9, CXCL10, CXCL11, CXCL12, CXCL13, and CXCL14, lacking the ELR amino acid motif (ELR−), can inhibit tumor angiogenesis." (PMID 34497764, 2021). "Our results demonstrated that CXCL13, FCRLA, MS4A1, and PLA2G2D have a negative correlation with tumor purity in OC." (PMID 34395521, 2021). "Immunohistochemical analysis revealed that the tumor cells were positive for CD21, CD35 and CXCL-13, focal positive for CD23, while negative for D2–40, CK, P63, CD30, SALL4, PLAP, EBV-LMP-1." (PMID 30646936, 2019). "Immunohistochemical staining showed that tumor cells in both areas were positive for CD21, CD23 and D2–40, while negative for CD35, CXCL-13, CK, P63, CD30, S-100, EBV-LMP-1." (PMID 30646936, 2019). "As grouping by the serum CXCL13 level and GPS was not independently prognostic for survival outcomes, the subgroup analysis was done according to tumor burden." (PMID 25966773, 2015). "CXCL13 is the ligand for CXCR5, and serum and ascites levels of murine, but not human, CXCL13 showed a striking elevation in tumor-bearing mice, with levels as high as 200,000 pg/ml in ascites, as measured by ELISA." (PMID 23936541, 2013). "Within tumor, blood-matched TCR phenotypes were predominantly not proliferating, but were instead consistently cytotoxic (GZMB+ and GZMK+ for CD4+, also GZMK+ and MAIT for CD8+), and also included noncytotoxic CXCL13+ CD4+ and Tregs as observed above." (PMID 40299576, 2025).
tumor (continued). "While CXCL13‐overexpression did not significantly alter CAR T cell accumulation in the spleen, it markedly enhanced CAR T cell infiltration into both the tumor‐draining lymph nodes and tumor sites." (PMID 40492496, 2025). "Finally, spatial transcriptome analysis revealed CXCL13 and CD8 expressions within tumor area clusters but not in adjacent normal areas, suggesting specific overexpression of CXCL13 in primary OSCC tissues." (PMID 39344390, 2024). "Tumors with brisk/non-brisk tumor-infiltrating lymphocytes (TIL) vs. absence of TIL exhibited significantly higher levels of APRIL/TNFSF13 (p = 0.01), CCL19 (p = 0.01) and CXCL13 (p = 0.01), but no such difference was observed for patients’ serum levels of CXCL10 (p = 0.97)." (PMID 37435077, 2023). "All in all, these results highlighted the relevance of the expression of chemokines such as CXCL13 and the lack of expression of the transmembrane oncoprotein MUC-1 as surrogate markers of the anti-tumor immune response mediated by activated lymphocytes in the TME." (PMID 36765559, 2023). "Intratumoral CD8+ T cells were enriched in CXCL13 and CCL4 expression, mediators of immune cell recruitment, although whether this has a positive or negative influence on tumor growth is unclear." (PMID 36253784, 2022). "Accordingly, we analyse the cytokine expression changes (more than 1.5 log2, 2.8 fold, p < 0.05, t-test) between No take and Take tumours and found a large series of chemokine/cytokine overexpressed in the No take samples, among them IFNG, CXCL13, CXCl9, CXCl11, CXCL10 and CCL5." (PMID 28588211, 2017). "The lack of prognostic significance of CXCL13 and GPS in patients with high tumor burden might be related with a strong correlation of elevated CXCL13 and GPS 2 with stage III/IV and detectable EBV in this study." (PMID 25966773, 2015). "Other chemokines, such as SDF-1, have been shown to directly induce tumor cell growth in non-AIDS-related cancers, and it is possible that CXCL13 could be doing so, also." (PMID 21490903, 2010). "While tumor diameter, nodal status and MUC-1 expression were similar in the two groups, the group exhibiting five immune markers contained higher HLA-DR contents (p < 0.0001) and CXCL13 expression levels (p = 0.001) than those with none of the selected markers." (PMID 36765559, 2023).
cancer (246 papers, 2008 to 2026). A tumor composed of atypical neoplastic, often pleomorphic cells that invade other tissues. "TIGIT, LAG3, PDCD1, and CXCL13 were highly associated with different stages of cancers, especially in KIRC and THCA." (PMID 40076932, 2025). "Systemic modulation of TLSs through strategies such as CXCL13 blockade, or conversely, CXCL13‐encoding mRNA or viral vectors, holds promise for either suppressing pathogenic TLSs or enhancing their formation in cancer immunotherapy settings." (PMID 40996881, 2025). "TLR4 and TLR7 agonists, including LPS and GS‐9620, have also been implicated in TLS neogenesis by enhancing CXCL13 expression and lymphoid aggregation in cancer and viral hepatitis models." (PMID 40996881, 2025). "CXCL13, expressed by stromal cells and macrophages, is a key chemoattractant for B cells and has been implicated in cancer development." (PMID 40943634, 2025). "In contrast, CXCL13 was negatively associated with PEBP1/STK11 co-expression in almost all cancer types." (PMID 40806276, 2025). "Among these IRATs, many studies have highlighted TRTs CXCL13+ T cells (CD4+/CD8+) as targets for cancer immunotherapy due to their association with improved clinical outcomes in many cancers." (PMID 40054456, 2025). "This indicates that the serum CXCL13 level is elevated in association with cancer, indicating its potential utility as a novel diagnostic and prognostic marker for OSCC." (PMID 39344390, 2024). "We identify essential cell populations in tertiary lymphoid structure, including CXCL13+ cancer-associated fibroblasts, stem-like CXCL13+CD8+ T cells, and B and T follicular helper cells." (PMID 39231979, 2024). "CCL3 on CD8+ T cells was also predicted to interact with CCR1 or CCR5 on myeloid cells and CXCL13 on CD8+ T cells was predicted to interact with CXCR5 on B cells or ACKR4 on cancer-associated fibroblasts." (PMID 39478117, 2024). "Hypoxia induces the cancer-associated myofibroblasts to release cytokines such as CXCL13 which are an inducer of cancer progression." (PMID 36787054, 2023). "CD8+ and CD4+ T cells, cancer-associated fibroblasts, cancer cells, and dendritic cells are able to secrete CXCL13, and CD8+ and CD4+ T cells, B cells, and cancer cells express CXCR5." (PMID 35053457, 2022). "The overexpression of CXCR5 and its cognate ligand CXCL13 has been implicated in many different types of cancer." (PMID 35978426, 2022). "Pan-cancer prognostic analyses indicated that CXCL13 was associated with better survival in BLCA, BRCA, HNSC, LUSC, OV, SKCM, and UCEC but a worse prognosis for GBM, KIRC, KIRP, and THYM by using Kaplan-Meier method and univariate cox regression analysis." (PMID 35141160, 2022). "They observed CXCL13 expression on cancer-associated fibroblasts, as assessed by immunofluorescence and real-time PCR." (PMID 35053457, 2022). "The CXC chemokine ligand‐13 (CXCL13) is a chemoattractant of B cells and has been implicated in the progression of many cancers." (PMID 34427969, 2021). "Cancer-associated fibroblasts can convert to myofibroblasts and secrete CXCL13 into the TME upon hypoxia and TGF-β stimulation." (PMID 34947813, 2021). "Under androgen ablation therapy, regressing PC is accompanied by cell death and hypoxia, which activates cancer-associated myofibroblasts (CAMF) to secrete CXCL13 by inducing HIF-1 activation and TGF-β expression." (PMID 34947813, 2021). "It was previously demonstrated that CXCL10, CXCL13 and other chemokines are closely associated with the occurrence and development of cancer." (PMID 32236620, 2020). "Most members of the chemokine family, including CXCL1, CXCL2, CXCL5, CXCL9, CXCL10 and CXCL13, where they are secreted by cancer or stromal cells, such as cancer-associated fibroblasts (CAFs) and dendritic cells (DCs)." (PMID 30925930, 2019). "To clarify the effect of CXCL13 on B lymphocytes, we analyzed the proportions of IgG subclasses, which were reported to be associated with many cancers' progression." (PMID 26161394, 2015).